ATG5 (autophagy related 5)
Diseases named in the same sentence as ATG5 in open-access papers (continued):
Sharing a sentence is not in itself a finding about the gene and the disease.
tumor (continued). "Moreover, at the end of the 21-day period, the expression levels of the autophagy-related molecules LC3, Atg5-12 complex, and Beclin-1 were significantly higher in tumor tissues from mice subjected to IMQ treatment combined with IR exposure." (PMID 28212561, 2017). "Importantly, inhibition of autophagy in TH9 cells enhances their anticancer functions in vivo, and mice with T cell-specific deletion of Atg5 have reduced tumour outgrowth in an IL-9-dependent manner." (PMID 28916785, 2017). "Approximately 77.4 % of the ESCC tumor samples tested positive for ATG5." (PMID 29207660, 2017). "In addition, myeloid cell-specific deletion of Atg5 resulted in the suppression of tumor dissemination to the peritoneal cavity upon splenic injection of MC38 tumor cells." (PMID 28686632, 2017). "Finally, the blockade of autophagy enhances TH9 cell anticancer functions in vivo, and mice with T cell-specific deletion of Atg5 have reduced tumour outgrowth in an IL-9-dependent manner." (PMID 28916785, 2017). "Both up-regulation and down-regulation of ATG5 have been demonstrated in various tumor tissues." (PMID 29207660, 2017). "However, a role of BFA in theactivation of CHOP was very little in TC-1 tumor cells and Atg5+/+ andAtg5−/− MEF cells.The results indicated that ER stressors initiate apoptosis of TC-1 tumor cells throughthe activation of the caspase-12/caspase-3 pathway." (PMID 28904818, 2017). "Furthermore, increased expression of ATG5 was observed in ESCC tumor tissue as compared to adjacent normal tissue." (PMID 29207660, 2017). "Interestingly, tumor spheres expressed the significantly lower level of ATG5, ATG7, BECN1 and LC3B mRNAs." (PMID 27934912, 2016). "In addition, genetic autophagy inhibitor ATG5 siRNA blocked metformin mediated tumor cell death of A549 cells induced by TRAIL." (PMID 26992204, 2016). "Interestingly, expression of Atg5 co-localized with Ad hexon protein, providing additional proof that the region of the tumor tissues treated with dl/shMet4+5 represents autophagic cell death." (PMID 25726528, 2015). "During oncogenesis in genetically engineered mice, reduced hemizygous expression of genes required for autophagy (BECN1, Atg4, ATG5, Atg7) can accelerate spontaneous or chemically induced tumor formation, suggesting that autophagy can serve as a tumor suppressor." (PMID 26247722, 2015). "In addition, intratumoural injection of ARL67156 increased the radiosensitivity of ATG5-deficient (ATG5KD) tumour cells in an immunocompetent context, indicating that it restored the immune response to irradiated ATG5KD CT26 tumour cells." (PMID 24037090, 2014). "Considering that IR-induced tumour cell death in vitro fails to explain some clinical observations in vivo, we decided to evaluate the effect of ATG5 and Beclin 1 depletion on the growth of irradiated A549 tumour xenografts implanted in immunodeficient BALB/c nude mice (which lack T lymphocytes)." (PMID 24037090, 2014). "Consistent with these in vitro findings, ATG5 OE CAR-T cells exhibited enhanced antitumor efficacy in vivo under IR-preconditioned settings, characterized by improved tumor control and survival, which was associated with sustained effector function of tumor-infiltrating CAR-T cells." (PMID 42099602, 2026). "We have reported that overexpression of Atg5 could suppress Ha‐ras‐induced tumor formation." (PMID 38826147, 2024). "In the context of tumor environment, spermidine either intrinsically or in a paracrine manner favors M1 polarization through Nos2 transcription thereby inhibiting tumor growth, while spermine inhibits M1 but promotes M2 polarization, through enhancing autophagy by ATG5 upregulation." (PMID 39717382, 2024). "Correspondingly, the content of ATG5 at both mRNA (assessed by qRT‒PCR assay) and protein levels (assessed by IHC staining and western blotting assay) were significantly upregulated in tumor tissues following the injection of Exo-Ts, which led to an enhancement of autophagy in tumor tissues." (PMID 37474520, 2023).
tumor (continued). "In addition, the role of SNHG16, another lncRNA, in inducing migration and autophagy through upregulating ATG5 was reviewed, and this molecule may also be affecting tumour growth, proliferation and migration steps (steps 1–2 and 4)." (PMID 36983973, 2023). "In the present study, we first found that ATG5 is expressed in an opposite pattern to miR-205-5p in HCC tumor tissues and cell lines, and the results of dual-luciferase reporter assays identified that miR-205-5p could inhibit the transcription of ATG5 by binding directly to its 3′UTR." (PMID 37474520, 2023). "In addition, we verified through in vivo experiments that overexpression of circTGFBR2 in HCC could upregulate the expression of ATG5 in tumor tissues, which enhances autophagy in tumor cells and promotes tumor progression." (PMID 37474520, 2023). "Additionally, our in vivo study revealed that ATG5 silencing could diminish CAFs’ promotive effects on xenograft tumor growth and lung metastasis." (PMID 37000314, 2023). "Indeed, their mutations in Beclin-11, ATG5 and ATG7 promotes tumor initiation." (PMID 35884904, 2022). "In this regard, a study reports the tumor-promoting effect of autophagy in K-Ras [K-Ras(V12)]-induced malignant cell transformation, where inhibiting ROS with antioxidants reduced K-RasV12-induced induction of Atg5 protein and Atg7 protein, autophagy, and cancer growth." (PMID 35359388, 2022). "Therefore, exploring the molecular mechanism of ATG5 may provide a novel strategy of anti-tumor treatment for LUSC." (PMID 34253689, 2021). "Therefore, the depletion of Atg5 in ECs could intensify the abnormality in the function of tumor vessels indicating the pivotal role of autophagy in ECs homeostasis." (PMID 32426106, 2020). "Furthermore, CDKL3 may promote tumor profession, invasion, metastasis, and prohibit tumor apoptosis partly by ATG5 activation." (PMID 32974198, 2020). "Furthermore, the tumors that formed in Atg5 heterozygous mice contained greater numbers of pro-tumorigenic M2-macrophages than control mice, and Atg5 heterozygous primary tumor cells had up-regulated expression of cytokines that regulate macrophage chemoattraction and differentiation into M2." (PMID 32344698, 2020). "Autophagy-related genes LC3-II and Atg5 may suppress tumor growth by inducing autophagy." (PMID 32398958, 2020). "Furthermore, inhibition of autophagy in HCT116 by ATG5 knockdown attenuated tumor growth in vivo." (PMID 32716961, 2020). "On the other hand, autophagy may protect tumor cells by providing extra arginine in the microenvironment of a liver-specific Atg7 or Atg5 deletion mice model, thereby indicating that autophagy partially compensates for nutrient loss in such condition and thus promotes cell growth." (PMID 33260729, 2020). "Notably, although genetic loss of Atg5 in ECs delays melanoma growth, it does not affect metastasis and tumor oxygenation." (PMID 30692642, 2019). "CQ improved both vessel structure and maturation, whereas the conditional knockout of the crucial autophagy gene Atg5 in endothelial cells (ECs) did not, thus highlighting a potential differential role for EC-associated autophagy and the lysosomes in pathological tumor angiogenesis." (PMID 30949450, 2019). "The fact that ATG5 is selectively inactivated by somatic mutations and/or alternative mRNA splicing, and that ATG16L2 is transcriptionally overexpressed, relative to ATG16L1, in multiple tumor types, suggests that the inhibition of autophagy is indeed oncogenic." (PMID 31636955, 2019). "Most importantly, we find in multiple tumor types that ATG5 somatic mutations and alternative mRNA splicing specifically disrupt the ATG16L1-binding pocket in ATG5 and impair the essential ATG5-ATG16L1 interactions that are initially required for ATG12–ATG5 conjugation." (PMID 31636955, 2019).
tumor (continued). "Specifically, depletion of autophagy related 5 (ATG5) or autophagy related 7 (ATG7) (loss of autophagy), or acyl-CoA synthetase short chain family member 2 (ACSS2) (acetate recapture loss) is well tolerated by most cells in culture, but can dramatically decrease tumor growth in vivo." (PMID 30104199, 2018). "In Atg5+/+ tumors, autophagic flux was increased in CR-fed relative to control-fed mice, suggesting that the prosurvival effects of autophagy induction may mitigate the tumor suppressive effects of CR." (PMID 27651895, 2016). "However, the initiation of KRas(G12D)-driven lung tumors in these mice was accelerated by ATG5 deletion, emphasizing that autophagy may prevent oncogenesis, but promote tumor growth." (PMID 25617802, 2015). "Knock down of Beclin1, ATG5 or LAMP2 reduced autophagosome and autolysosome formation, and tumor cell killing." (PMID 41954991, 2026). "In vivo, co-administration of the sh-RPS6KA2 plasmid and cisplatin significantly increased the expression of ATG5, ATG7, and BECN1, as well as promoted subcutaneous tumor growth compared to cisplatin monotherapy." (PMID 41502518, 2025). "Promoter hypermethylation and histone deacetylation can silence ATG5, BECN1, and LC3B, thereby suppressing autophagy and promoting tumor survival." (PMID 41329030, 2025). "In contrast, administration of the RPS6KA2 overexpression plasmid together with cisplatin reduced the expression of ATG5, ATG7, and BECN1 and inhibited tumor expansion." (PMID 41502518, 2025). "Enhances radioresistance by sequestering miR-372-3p to induce ATG5/ATG12-dependent autophagy, enabling tumor cell recovery after radiotherapy." (PMID 41409273, 2025). "Meanwhile, sphere formation, colony formation, transwell, and in vivo tumor growth assays showed that both HCQ treatment and ATG5 silencing significantly mitigated the inhibitory effects of betaine on these cellular phenotypes." (PMID 39897540, 2025). "Almost all solid tumors highly express ATG5, ATG7, ATG6L1, and secretion-related genes such as RABs, revealing the interaction between tumor progression and intracellular cargos transport." (PMID 39893499, 2025). "Conditional knockout of Atg5 in α-SMA+ CAFs promoted inflammatory re-programming in CAFs, reduced Treg cell infiltration and attenuated tumour development." (PMID 38862534, 2024). "In vivo, the volume of tumours in the Har group was decreased, and immunohistochemistry revealed decreased levels of Ki-67 and GPX4 and increased levels of ATG5 and NARL3." (PMID 38499622, 2024). "We demonstrated their role in the PTT-induced execution of autophagy that progressed through ATG5/ATG7, which was reversed and increased the survival of tumor cell populations by silencing them." (PMID 39409987, 2024). "We investigated the expression of key autophagy proteins ATG5, LC3, and P62 in tumor tissue to evaluate potential Abi and autophagy inhibitors for future PCa treatment." (PMID 39409882, 2024). "In a fashion similar to that observed for autophagosome formation, knock down of Beclin1 or ATG5 reduced the lethality of GZ17-6.02 and abolished the dose-dependent effect on tumor cell killing." (PMID 38329728, 2024). "Moreover, a single‐gene alteration, such as Atg5 under autophagy‐deficient conditions, might not be sufficient to induce a long‐term tumorigenic promoting effect capable of forming a tumor." (PMID 38826147, 2024). "While we observed a downregulation of autophagy upon vascular disruption and subsequent local inflammation in BON cells, an upregulation of LC3B, ATG5, and LAMP1 was detected under multi-chemotherapeutic conditions in the NCI-H295R tumor model." (PMID 36980669, 2023). "NORAD acts as a sponge for miR‐433‐3p, upregulating the expression of downstream target genes ATG5 and ATG12 to increase autophagic flux and improve tumour cell resistance to L‐OHP." (PMID 37837401, 2023).
tumor (continued). "Nevertheless, the autophagic factors ATG5 and ATG7 were found to display reduced expression in CM tissues compared to benign nevi, thus indicating a tumor suppressive role of autophagy in early-stage CM." (PMID 37386023, 2023). "IHC analysis showed PCK1 and ATG5 was up-regulated, while P62 and p-UBAP2L Ser454 expression was down- regulated in PCK1-OE tumor tissues." (PMID 37062825, 2023). "Sox2OT‐V7 can promote autophagy of tumour cells through the Sox2OT‐V7/miR‐22‐3p/ULK1 axis and Sox2OT‐V7/miR‐142‐5p/ULK1, ATG4A and ATG5 axis, mediating drug resistance to DOX." (PMID 37837401, 2023). "Whereas IRE1 and PERK pathways can induce changes in autophagy-related markers such as increased Atg5, LC3-II, etc., to promote autophagy, which inhibits ERS-induced apoptosis in tumour cells." (PMID 38044941, 2023). "Collectively, our study results indicate that USP13 promotes glycolysis and tumor progression in OS by stabilizing METTL3, thereby stabilizing ATG5 mRNA and facilitating autophagy in OS." (PMID 37151889, 2023). "Phosphorylation of ATG5 at Thr101 in GBM is positively regulated by PAK1 acetylation, which promotes tumor growth." (PMID 37143582, 2023). "We further show that inhibiting autophagy by genetical ablation of FIP200, Atg5 or Atg7, significantly inhibited LAS tumor cell proliferation in vitro and tumorigenicity in vivo." (PMID 36813768, 2023). "The acetylation of the hypoxia‐induced autophagy regulator PAK1 regulates the phosphorylation of ATG5 at Thr101 in GBM and is important for hypoxia‐induced autophagy and tumor growth." (PMID 37143582, 2023). "All together, our data show that TINCR activates the transcription of ATG5 by interacting with PTBP1, leading to LCSC self-renewal and tumor propagation." (PMID 36385098, 2022). "Loss of CRL4CUL4A/DDB1 significantly inhibited peritoneal seeding and tumor growth of A2780CP cells, whereas ATG5 depletion partially protected A2780CP cells from cell death, as measured by bioluminescence." (PMID 36481655, 2022). "Of these, five candidate tumor-suppressor genes, including FOXO3, HACE1, PRDM1, ATG5, and AIM1, were identified in the minimal region in del 6q21." (PMID 35054466, 2022). "While CREBRF suppresses tumor progression by downregulating CREB3 and ATG5, NR3C2 inhibits cancer cell survival and migration through repression of β-catenin and c-Myc." (PMID 36358691, 2022). "To test this possibility, we investigated host tumor microenvironment following the inoculation of KRASG12V;Atg5+/+ and KRASG12V;Atg5∆/∆ tumor cells, respectively, into different genotypic recipient mice (Atg5+/+ and Atg5flox/flox)." (PMID 35966597, 2022). "It means dysfunction of tumor-infiltrating cytotoxic T lymphocytes (CTL) and rejection of CTL by immunosuppressors are stronger in ATG5 high expression HNSCC, and the ICB efficacy is worse." (PMID 36185455, 2022). "For example, in osteosarcoma, miRNA-22 can inhibit the expression of ATG5, Beclin1, and LC3, which can enhance the sensitivity of tumor cells to chemotherapy." (PMID 35136409, 2022). "Both ATG5 and LC3II has been identified as an autophagy substrate and promoted tumor progression under diverse autophagy conditions." (PMID 36008375, 2022). "We screened the genes ATG10 and ATG5 related to autophagy enrichment for further testing and found that only ATG10 was significantly up-regulated in NPC cells and tumor tissues (all p < 0.05)." (PMID 34980191, 2022). "It was found that the protein levels of ATG5 and LC3-II in tumor tissues from the sh-FEZF1-AS1-SGC7901 group was much lower than those from the sh-NC-SGC7901 group when treated with 5-FU." (PMID 34790665, 2021). "In a murine GC xenograft model, ASIC1 or ATG5 gene knockdown inhibited the growth of the tumor cells, whereas ASIC1 shRNA treatment led to decreased tumor volumes and prolonged survival times of the animals." (PMID 33856653, 2021).
tumor (continued). "Results of present study showed that the expression of ATG3, ATG5 and LC3‐II was increased in the metformin‐treated cells, indicating that autophagy was involved with the anti‐tumour effect of metformin." (PMID 34164906, 2021). "HAGLROS inhibits apoptosis and promotes autophagy to regulate tumor biological behavior mainly via the PI3K/AKT/mTOR and miR-100/ATG5 pathways." (PMID 34692467, 2021). "We further evaluated the protein expressions of autophagy markers (ATG5, ATG7, Beclin-1, and LC3 B) and necroptosis markers (RIPK1, RIPK3) in NGP xenograft tumor tissues after rapamycin and MK-2206 combination treatment by Western Blot." (PMID 32116708, 2020). "Meanwhile, mRNA level of LC 3 was remarkably decreased in the tumor tissue of the BJE-H group, and a declining trend was also observed for ATG13 and ATG5." (PMID 32411003, 2020). "ESCC tumor tissues possessed a significantly higher expression of CDKL3 and autophagy-related gene 5 (ATG5) than matched adjacent normal tissues." (PMID 32974198, 2020). "ATG5 and ATG7 have previously been reported to be the mutual targets of different lncRNAs for regulating autophagy in several tumor cells." (PMID 33230459, 2020). "Tumor tissues and adjacent normal tissues from ESCC patients were immunostained for expression of CDKL3 and ATG5, both of which were predominantly localized in the cytoplasm." (PMID 32974198, 2020). "Our results from 46 paired tumor and normal adjacent tissues indicated that CDKL3 and ATG5 were, respectively, high-expressed in 32 of 46 (69.56%) and 41 of 46 (89.13%) cases of ESCC, which was statistically higher than that in the adjacent non-tumor tissue." (PMID 32974198, 2020). "In these mouse models, essential autophagy genes, such as ATG5, ATG7, ATG13 or ULK1, are deleted in genome of tumor cells that arise spontaneously in the context of a normal tumor microenvironment and functional immune system." (PMID 32308763, 2020). "We also assessed LC3, ATG5, ATG16L1 and p62 protein expression levels in tumours derived from HepG2/miR-142-3p and HepG2/control xenografts after sorafenib therapy." (PMID 29472524, 2018). "We have observed reduced expression of ATG1, ATG5, and ATG16L1 as well as decreased LC3B and elevated p62 levels, suggesting a diminished basal autophagy in TGCT and a likely tumor-suppressive function of autophagy in the tumorigenesis of TGCT." (PMID 30245976, 2018). "This group also showed that the impairment of tumor growth was dependent on the cellular immune system as well as on autophagy; IF + chemotherapy could not impair tumor growth in either athymic nu/nu mice or tumor cells after autophagy deficiency was induced by Atg5 knockdown." (PMID 30540126, 2018). "Ginsenoside 20(S)-Rg3 treatment suppressed tumor growth while upregulating LC3II, ATG5, and ATG7 levels." (PMID 29209152, 2017). "Over-expression of ATG5 in ESCC cells is possibly correlated with autophagic events which induce drug resistance and tumor growth to lead to poor prognosis." (PMID 29207660, 2017). "Silencing of Sirt3 expression markedly blunted autophagic response in the tumor cells subjected to hypoxia, as determined by a decrease in LC3-II and Atg5–12 complex, and an increase in p62 protein." (PMID 27270321, 2016). "Silencing the expression of autophagy-related genes ATG5, LC3 or p62 in HeLa and A549 cells gave similar results, suggesting that autophagy is required for Spred2-induced tumor cell death." (PMID 27028858, 2016).